ACTA2 (actin alpha 2, smooth muscle)
Diseases named in the same sentence as ACTA2 in open-access papers (continued):
Sharing a sentence is not in itself a finding about the gene and the disease.
tumor (223 papers, 2007 to 2026). "ACTA2 was highly expressed in this region, indicating that the tumor cells were closely linked to myofibroblasts and CAFs." (PMID 39639005, 2024). "The transition is defined by genes associated with the tumor micro-environment and ACTA2 as a key indicator for the involvement of CAFs." (PMID 37190121, 2023). "In human GBM specimens, ECM-rich zones bordering cellular tumor regions and around blood vessels are characterized by high expression of smooth muscle actin (encoded by ACTA2), suggesting the contribution of mesenchymal stromal cells to ECM deposition." (PMID 37292803, 2023). "There was a trend towards upregulation of genes encoding fibroblast activation markers (Col1a1, Mrc2, Acta2) in the presence of tumor-infiltrating CD8+ T cells." (PMID 38259467, 2023). "Cancer-associated fibroblast (CAF) is often used as a synonym for ACTA2+ fibroblasts in the tumor stroma." (PMID 37190121, 2023). "The quantification of mesenchymal cells (ACTA2+), and tumor associated microglia/macrophages (TAM) cells (CD68+ and IBA1+) showed a significant enrichment of these populations within oncostreams compared to the surrounding areas." (PMID 35750880, 2022). "To our surprise, we found that Mmp2 with metalloprotease-2 as the end product, and Acta2 encoding for α2-smooth muscle actin, are also underexpressed in tumor cells." (PMID 34737944, 2021). "ACTA2 was associated with maintenance of cell shape and mechanical tension and played an important role in tumor cell migration and invasion." (PMID 33384961, 2020). "Similar to myofibroblasts in wounds or fibrotic tissues, tumor-associated fibroblasts are known to overexpress ACTA2, FAP and PDGFRB." (PMID 30473751, 2018). "In contrast to MTX tumors, functional enrichment of non-MTX sCRC tissues showed inhibition of those genes associated with invasive sCRC tissues such as ACTA2, together with up-regulation of tumor suppressor genes (e.g. miR-3178)." (PMID 29296198, 2017). "On the other hand, it has been reported that TGF-β1 is able to significantly increase Acta2 expression in both normal and cancer associated fibroblasts cultures, which are believed to promote tumor growth and progression." (PMID 21481241, 2011). "Interestingly, fibroblasts from KPTN tumors were enriched with populations (clusters 6–8) that highly expressed Acta2, Spp1, and Sdc1, which were associated with a tumor-promoting fibroblast phenotype." (PMID 41480763, 2026). "In addition, single-cell RNA sequencing data showed that Acta2 is a myofibroblast marker associated with tumor progression and fibrosis." (PMID 39720517, 2024). "The mechanism may be that ACTA2 stimulates the release of IL-6 from tumor-associated fibroblasts (CAF), induces epithelial-mesenchymal transformation (EMT), and induces the transformation from non-invasive tumor type to invasive tumor type." (PMID 37274283, 2023). "Consistent with this hypothesis, increased tumor-stroma interactions were associated with increased mRNA expression of both ACTA2 and PECAM1." (PMID 36647832, 2023). "In addition to EMT, invasion and metastasis of cancers including urothelial cancer require an interaction between the tumor cells and the cancer associated fibroblasts that express ACTA2." (PMID 36293167, 2022). "These tumor-associated myofibroblasts express ACTA2 and PDGFRα/β." (PMID 28806761, 2017). "The high correlation between the six extracellular matrix-associated lncRNAs with CAF markers FAP and ACTA2 may suggest a role for lncRNAs in the acquisition of an activated phenotype by fibroblasts in the tumour stroma." (PMID 27685983, 2016). "The wider distribution of PTEN expression in quartile one of ACTA2 expression also supports the hypothesis of tumour PTEN loss being more prevalent than previously estimated." (PMID 25608477, 2014).
tumor (continued). "In addition, genes involved in cell differentiation and apoptosis (PDZK1) and genes encoding actin and actin-binding proteins (CNN1, ACTA2) were also downregulated in both types of tumor cells." (PMID 17389037, 2007). "As principal components of tumor stroma, CAFs were identified using α-SMA—a canonical marker for CAFs, which is encoded by the ACTA2 gene." (PMID 41551463, 2026). "Four primary cell populations were first identified using canonical cell markers: WT tumor cells (WT1, NCAM1, SIX1, SIX2, PAX2), cancer-associated fibroblasts (CAFs) (ACTA2, TAGLN, COL1A1, PDGFRB), endothelial cells (PECAM1, CLDN5, ENG, VWF) and immune cells." (PMID 40098972, 2025). "Integration of the Wnt1 scRNA-seq data revealed tumor-specific fibroblast clusters (C4W, C7W, C9W, and C10W) that were marked by expression of Acta2 and Tnc, and included a cycling cluster (C10W)." (PMID 40216939, 2025). "Specifically, ALB and CYP2E1 were highly expressed in normal areas, GPC3 and AKR1B10 were highly expressed in tumor areas, ACTA2 and COL1A1 were highly expressed in fibrostic areas, and PTPRC was highly expressed in inflammation areas." (PMID 40051627, 2025). "This confirmed that stromal transcripts (Fap and Acta2) were mapped to the mouse genome, while tumor cell-intrinsic transcripts (MUC1 and KRT19) were human reads." (PMID 40508010, 2025). "Late-stage CAFs showed enrichment for Rgs5, Nfkb pathway, Serpins (a1d,a3f, e2, and i1), Timp1, Acta2 expression, and vCAF signatures, while Pdgfrb decreased with tumor progression." (PMID 38525245, 2024). "State0 (Cd34− CAF) represents a more differentiation state with the tumor-prone signature marker such as Acta2." (PMID 39401181, 2024). "All examined fibrotic markers α-SMA (Acta2), Col1A1, and Col4A1 and proliferation markers are also dramatically increased in the tumor." (PMID 39796711, 2024). "Focusing on CAFs, our analysis revealed a novel subpopulation marked by CD34+PI16+, which gave rise to the classical ACTA2+MCAM+ CAFs in tumor, also known as myCAF (data unpublished)." (PMID 39401181, 2024). "A unique molecular signature intrinsic to oncostreams, with overexpression of key genes (i.e., COL1A1, ACTA2) that drive the tumor's mesenchymal transition and malignancy is also identified." (PMID 38384234, 2024). "Fibroblasts in the tumor showed an activated phenotype with α-smooth muscle actin (α-SMA or ACTA2) expression and stained 6-16% of the tumor surface area." (PMID 39051113, 2024). "For example, ACTA2+CAFs are essential for restricting tumour invasion and progression in mouse pancreatic ductal adenocarcinoma models, yet promoting tumour progression in some cases, at least partially via influencing TME remodelling." (PMID 38158643, 2024). "Western blot and qRT-PCR analyses showed that POSTN and CAF activation marker Acta2 expression were up-regulated in CAFs co-cultured with IHH-4 or TPC-1 tumor cells compared with CAFs cultured alone." (PMID 38773979, 2024). "Many of the DEGs were involved in ferroptosis (Ptgs2), enhanced T-cell function (Lef1), regulators of EMT (Zeb1, Zeb2, Vimentin, and Sfrp2), and fibrosis (Col1α1 and Acta2) in the tumor microenvironment." (PMID 36835036, 2023). "Lastly, smooth muscle contraction, actin filament-based processes, and vascular smooth muscle contraction were enriched in ACTA2+ myofibroblasts, which stimulate tumor progression via contraction of the ECM and promotion of EMT." (PMID 37430270, 2023). "Thereafter, we examined how ACTA2 expression correlates with the time to tumor recurrence and the mode of recurrence." (PMID 37891844, 2023). "The pulmonary RFX1 level negatively correlated with each of the two inflammatory signatures, whereas ACTA2 positively correlated with tumor inflammation." (PMID 37781522, 2023).
tumor (continued). "Cluster 8 ECs (COL1A1, COL1A2, COL3A1, PDGFRB, and ACTA2) showed an endothelium-mesenchymal transformation phenotype, contributing to tumor progression and metastasis." (PMID 37533434, 2023). "Combined PECAM1 and ACTA2 staining showed similar vessel (PECAM1+) area with similar coverage by pericytes (ACTA2+) in the tumor tissue of both WT and Apold1−/− mice." (PMID 36933174, 2023). "After intersecting genes in the yellow module of WGCNA with DEGs, we identified five myCAFs marker genes defined by previous single-cell sequencing that were significantly down-regulated in tumor tissues, including ACTA2, MYL9, TAGLN, TPM1, and TPM2." (PMID 35309916, 2022). "ACTA2 is one of the markers for myofibroblasts, and the IHC staining of ACTA2 confirmed that the proportion of myofibroblasts is higher in tumor tissues compared to adjacent normal tissues." (PMID 36104333, 2022). "Similar to the data from small tumours, the expression levels of Acta2 in the CAF cluster were significantly reduced in the large tumours grown in Atf4Δ/Δ mice." (PMID 35654839, 2022). "Through IHC assay, we verified the reduced ACTA2 expression levels in tumor tissues compared with the adjacent normal mucosa, indicating a decreased myCAFs abundance in BLCA tissue." (PMID 35309916, 2022). "For example, hypoxic conditions, which are typical for the tumor microenvironment, have been found to activate the expression of ACTA2 and some collagens in dermal fibroblasts." (PMID 36263012, 2022). "What collagen VI staining remained in Col6a1 KO tumours appeared to colocalise with αSMA (ACTA2)-positive cells, which likely represent myofibroblast-like resident cells." (PMID 36546396, 2022). "Then, we demonstrated the majority of fibroblasts expressed α-SMA (ACTA2) driven from tumor tissues." (PMID 36483553, 2022). "Beyond the tumour, expression of both Fap and Acta2 was observed in stromal cells across multiple tissues, whereas Lrrc15 was absent." (PMID 36171287, 2022). "In murine PDAC models, ACTA2 deletion has developed an undifferentiated tumor and promoted tumor progression." (PMID 35805064, 2022). "Tumor cells also express ACTA2 and in our study, exposure to As3+ resulted in an increase in expression of ACTA2 in some of the tumor cells as well as an increase in expression of ACTA2 in the fibroblasts associated with the tumor stroma." (PMID 36293167, 2022). "When directly co-cultured with tumor organoids, PSCs showed an elevated level of ACTA2 and myofibroblast-like phenotypes." (PMID 35805064, 2022). "Increased expression of CDH2, CTSB, ACTA2, MMP2 and ZEB1 was associated with increased myometrial invasion, and expression of CTSB and MMP9 was significantly associated with tumor recurrence." (PMID 34936030, 2021). "To further determine the effect of HIF‐1α expression on the activation of fibroblasts, we examined the effects of TGF‐β1, tumour cell CM and Cocl2 on Acta2 and Col1a2, which are markers of CAFs." (PMID 33943003, 2021). "Consistent with their expression in both myoepithelial and mesenchymal cells, expression of Pdgrfb and Acta2 were increased in residual tumor cells in both the HER2/neu and Wnt1 models." (PMID 34088357, 2021). "TGF‐β1, tumour cell CM and Cocl2 notably increased the expression of Col1a2 and Acta2 of fibroblasts at RNA levels." (PMID 33943003, 2021). "The expression level of the hub genes KDR and ACTA2 in tumor tissue were compared with their matched normal tissues, and survival curves were plotted." (PMID 34179721, 2021). "This is further supported by gene expression analysis, where CAFs isolated from Osm−/− tumours exhibited decreased inflammatory gene expression (e.g. Il6, Mmp3, Has2 and Osmr) but increased myofibroblast gene expression (e.g. Acta2, Itgav and Fn1)." (PMID 34921158, 2021). "To spatially identify putative CAFs within tumor tissue, we immunostained patient tumors with PDGFRα/β to label fibroblasts and pericytes, and ACTA2 to label activated tumor fibroblasts." (PMID 34884982, 2021).
tumor (continued). "As expected, genes associated with stroma were almost exclusively found in the mouse reads (Fap, Acta2), and tumor marker expression was found in reads mapped to the human genome." (PMID 31941932, 2020). "At gene level, the encoding gene of a-SMA, ACTA2, was also associated with clinicopathologic features including TNM stage, tumor size, tumor encapsulation, and vascular invasion." (PMID 33292459, 2020). "Adding a TGFβ-receptor-inhibitor to stellate cell – tumor cell co-cultures also reduced stellate cell activation, as measured by mRNA-expression of ACTA2 and collagen." (PMID 33103995, 2020). "In particular, the myofibroblast (Thy1+/Dcn+/Acta2+ (αSMA)) fraction which comprised 4.8% of all cells in the original tumor increased to 15.9% of the tumoroid cells." (PMID 32183351, 2020). "These factors have been showed to be involved in chemotaxis (CXCR485) and locomotion (ROCK1/2, Acta2, Pak-1, Rac1, and RhoA28) of stromal cells to help migration of these cells to tumor niches." (PMID 31391540, 2019). "Stromal DKK3 expression in human tumours positively correlated with the expression of CAF markers ACTA2, FAP and COL1A2, supporting a link between DKK3 and CAFs." (PMID 30631061, 2019). "A strong association was observed between high ACTA2/IL6 mRNA co-expression and tumor invasiveness (****P < 0.0001), correlating with our in vitro findings." (PMID 30744595, 2019). "LBR expression was relatively reduced in tumour stroma, in contrast to ACTA2 (smooth muscle actin), which was relatively high in tumour stroma." (PMID 31481734, 2019). "In terms of tumor angiogenesis, Acta2 served as a mature pericyte marker whereas Pdgfrb served as a marker for progenitor perivascular cells with the ability to differentiate into pericytes and regulate vessel stability and vascular survival." (PMID 28470822, 2018). "The most prominent epithelial cell population in each tumor expressed luminal cell and luminal progenitor markers, while in some tumors (e.g., tumor 89), a minority population was evident that expressed markers of myoepithelial cells including ACTA2 and TAGLN." (PMID 30181541, 2018). "RT-qPCR analysis of tumor revealed that doxorubicin induced ACTA2, VIM and SOX2 whereas addition of T12 reduced SOX2 expression." (PMID 29541394, 2018). "Using GIFM, we traced the fate of ACTA2-expressing cells in vivo during mouse tumor progression and found that the labeled cells are largely lost in PB-MYC tumors without changing fate and giving rise to cancer reactive stroma." (PMID 27935821, 2017). "ACTA2 staining revealed the SM layers were disrupted and the proportion of cells was decreased in most advanced tumor samples, whereas VIM was maintained in the remaining stromal cells." (PMID 27935821, 2017). "Double immunofluorescence of CD31 and ACTA2 further revealed blood vessel formation within tumor foci." (PMID 27344183, 2016). "Additionally, we performed survival analysis using the myofibroblast marker ACTA2 in TCGA, comparing normal and tumor tissues." (PMID 39891284, 2025). "Cluster C0, for instance, expressed high levels of matrix metalloproteinases (MMP13, MMP11) and alpha‐smooth muscle actin (ACTA2), a well‐known myofibroblast marker, signifying the presence of myofibroblasts known to promote tumour progression and angiogenesis." (PMID 38445456, 2024). "Thus, single targeting ACTA2 for anti‐tumour therapy resulted in variable efficacy, and possibly opposing." (PMID 38158643, 2024). "It is of higher importance that RGS5+ACTA2+ CAFs are present in all tumor samples, which might represent a general phenotype that is similar to activated fibroblasts expressing ACTA2 in non-cancerous conditions, such as wound healing." (PMID 39516494, 2024). "FCN3+ endothelial cells and ACTA2+ fibroblasts are significantly lost when the phenotype becomes metastatic, indicating that the blood vessels may be broken and the formation of tumor thrombus is promoted." (PMID 38824541, 2024).
tumor (continued). "Fibrogenesis in S‐ECM samples is likely due to the presence of an activated cancer‐associated fibroblast (CAF) population in the tumor microenvironment, as indicated by the identification of CAF marker genes as key regulators for S‐ECM, including FAP, ACTA2, PDGFRB, VCAN, and ITGA11." (PMID 36637997, 2023). "In addition, we were able to identify different populations of tumor capsule overexpressing cancer-associated fibroblasts (CAFs) markers such as FAP, VIM, and ACTA2 as well as hepatic stellate cells markers (HGF, LRAT, RGS5)." (PMID 37932266, 2023). "Moreover, PECAM1+ cells (ECs) in cluster 8 ECS (COL1A1, COL1A2, COL3A1, PDGFRB, and ACTA2) showed an endothelial-mesenchymal transformation phenotype, which contributed to tumor progression." (PMID 37533434, 2023). "These three types can be separated by the biomarkers of myCAF, which exhibits the high expression of ACTA2, FAP, and TGF-β, and low expression of IL6, which requires direct interaction with cancer cells in PDAC and might be associated with tumor progression." (PMID 36900272, 2023). "Furthermore, MDSCs contributed to ECM remodeling and vascular‐related gene expression in a subset of recurrent tumor CAFs, including ACTA2, TMP1, MMP2, and COL1A2." (PMID 37743226, 2023). "On-tissue quantitative analyses of 215 surgically resected PDACs have shown that the mean occupancy rate of collagen in tumor tissues was 38.4%, while that of fibroblastic cell populations expressing ACTA2 and/or FAP was 33.3% (unpublished data related to our previous analyses)." (PMID 35805064, 2022). "Next, we employed lineage-specific markers to annotate clusters into major cell types of the tumor, including T cells (CD3G, CD4, CD8A, CD28, and IL7R), B cells (CD19 and CD20), myeloid cells (HLA-DRA and CD14), fibroblasts (THY1 and ACTA2), and tumor cells (EPCAM and S100A)." (PMID 35634306, 2022). "This upregulated expression was validated by RT-qPCR analysis of cultured tumour cells and tumours cells isolated from in vivo tumours, although it is important to note that expression of both Acta2 and Mrc2 in the D2A1-m12 cells is still substantially lower than expression levels in CAF." (PMID 34112782, 2021). "Analysis of bulk tumour mRNA displayed a strong correlation between ACTA2, a marker of MSCs, and matrix remodelling enzymes (MMP2), ECM proteins (VCAN, FN1, COL1A1), immunomodulatory molecules (Serpine1, CXCL12), innate immune cell markers (CD14, ITGAX) and adaptive immune cell markers (CD4)." (PMID 34885111, 2021). "This, however, is probably caused by non-optimal tissue sampling from tumor bulk, as ACTA2-expressing myofibroblasts are located mostly at its border." (PMID 32630408, 2020). "Also, the human PSCs were activated by the co-cultured mouse tumour cells as indicated by increased ACTA2, COL1A1, FN and TGFB1 mRNA levels." (PMID 32460715, 2020). "However, when we checked the expression of several tumor less aggressiveness-related genes, such as ACTA2, FBLN1, F2R, we found that the expressions of these genes were increased upon overexpression of PAGE4." (PMID 30658679, 2019). "Interestingly, metastatic PCa samples expressed significantly lower levels of CNN1 and ACTA2 compared with primary tumor samples and normal." (PMID 27935821, 2017). "TGF-β1-mediated ACTA2 triggers tumor invasion during the EMT." (PMID 28881584, 2017). "A lack of an adequate amount of myofibroblasts collected of the tumour stromal compartment compared to the normal stromal compartment seems not to be the main cause since ACTA2 and FAP are also expressed in myofibroblasts and show an opposing result." (PMID 28531107, 2017). "Tumor-adjacent s1-CAFs highly express ACTA2 and TGFB1, thereby promoting ECM remodeling and immune exclusion, while s4-CAFs, which are associated with tertiary lymphoid structures, express high levels of HLA-II molecules and chemokines, supporting anti-tumor immune responses." (PMID 41445734, 2025).